C1QBP (complement C1q binding protein)
Diseases named in the same sentence as C1QBP in open-access papers (continued):
Sharing a sentence is not in itself a finding about the gene and the disease.
tumor (72 papers, 2007 to 2025). "Studies have revealed the potential role of C1QBP in various cancers, including breast and lung cancer, where its expression is linked to tumor invasiveness and prognosis." (PMID 40429658, 2025). "We demonstrated tumor cell-secreted Vtn interacts with C1qbp localized on the cell surface of tumor-associated macrophages, inhibiting phagocytosis of tumor cells and shifting macrophages towards the M2-like subtype in the tumor microenvironment." (PMID 38773982, 2024). "Complement component 1, q subcomponent binding protein (C1QBP), a promising molecular target, has been implicated in breast carcinogenesis." (PMID 36674861, 2023). "Collagen, C1QBP, tumor-associated fibroblasts), which is more similar to the patient tumor than PDO, which are lacking these components." (PMID 35740561, 2022). "C1QBP overexpressed in a variety of tumor cells is implicated in tumor malignant progression and tumor therapeutic treatment." (PMID 36467687, 2022). "C1QBP expression is also strongly associated with tumor cell proliferation, chemotaxis, and cancer metastasis." (PMID 36555540, 2022). "Additionally, the loss of C1QBP leads to impaired T cell function, weakening the tumor’s immune response capability." (PMID 40429658, 2025). "Therefore, a thorough investigation of the molecular pathways that underlie C1QBP-mediated tumor progression is crucial for providing biological and mechanistic insights, that would be valuable for developing effective treatment strategies." (PMID 36674861, 2023). "Additionally, C1QBP has been shown implicated in mitochondrial-dependent apoptosis of tumor cells." (PMID 36467687, 2022). "In vivo, orthotopic OSCC models showed Pa28γ overexpression increased tumor growth and elevated C1qbp levels, correlating with elevated ATP and ROS." (PMID 40736231, 2025). "After harvesting the tumour tissue, we employed immunohistochemistry (IHC) and western blot techniques to assess the expression of C1QBP protein in different treatment groups in vitro." (PMID 39748215, 2025). "C1QBP exhibits heightened expression across a spectrum of tumours, thereby fostering their proliferation and metastasis, rendering it a pivotal therapeutic target." (PMID 39748215, 2025). "At the same time, apCAFs can also prevent T cells from apoptosis through the action of C1q and C1qbp, thus inhibiting tumor formation and exerting an anti-tumor effect." (PMID 40093895, 2025). "Sufficient energy is essential for cancer development, and C1QBP promotes malignant behaviors such as tumor invasion and metastasis by enhancing OXPHOS function in various cancers." (PMID 40736231, 2025). "The newly discovered peptide PDBAG1 is the first small molecule substance found to directly target and degrade C1QBP, demonstrating significant tumour inhibitory effects and therapeutic potential." (PMID 39748215, 2025). "Using transgenic Psme3-/- mice and subcutaneous tumor grafts, we confirmed that silencing of Pa28γ suppresses tumor growth, reduces C1qbp levels, and dampens mitochondrial metabolism—specifically in knockout hosts." (PMID 40736231, 2025). "Analyses of gene expression levels of the PPIF gene (for CypD) and C1QBP (for C1qBP) genes show parallel expression patterns in almost all tissues in normal and tumour states." (PMID 41401049, 2025). "The trend of ATP and ROS was consistent with tumor size, and the protein levels of C1qbp in the tumors were also reduced in the Pa28γ-silenced groups." (PMID 40736231, 2025). "C1QBP has been shown to play a significant role in cancer progression, as influencing tumor growth, invasion, and metastasis." (PMID 40736231, 2025). "Molecular biology experiments on tumor tissues from 5 LUAD patients revealed higher expression of C1QBP and PFKP in tumors compared to adjacent tissues." (PMID 41041346, 2025). "We identified a ligand-receptor pair of Vitronectin (Vtn) and complement C1Q binding protein (C1qbp) in tumor cells or macrophages, respectively." (PMID 38773982, 2024).
tumor (continued). "By illustrating how C1QBP influences macrophage polarization in the tumor microenvironment, our findings offer a promising new target for OS treatment strategies, potentially improving patient outcomes and combating drug resistance." (PMID 39553438, 2024). "Overall, these results suggest that Vtn-C1qbp is an anti-phagocytic signal that is capable of protecting tumor cells from phagocytosis by macrophages in vitro and in vivo." (PMID 38773982, 2024). "Our results showed that after knockdown of C1qbp, macrophages co-cultured with tumor cells significantly preferred the M1-like type." (PMID 38773982, 2024). "In subsequent experiments, we explored the effects and the underneath mechanism of Vtn-C1qbp regulating macrophage phagocytosis as well as tumor growth." (PMID 38773982, 2024). "To investigate the role of Vtn-C1qbp signaling in regulating the macrophage-mediated anti-tumor immune response, we knocked down Vtn in 4T1 cells and conducted phagocytosis assay using Raw264.7 and BMDM." (PMID 38773982, 2024). "We propose that there is a distinct mechanism regulating the transfer of C1qbp to the plasma membrane, potentially influenced by specific factors secreted by the tumor." (PMID 38773982, 2024). "By sorting out macrophages that had engulfed tumor cells by flow cytometry, and then mapping the genes that impeded macrophage phagocytosis in macrophages and tumor cells in cell-cell interaction database, we identified the ligand-receptor pair of Vtn-C1qbp." (PMID 38773982, 2024). "Based on such premises, C1QBP can be a target of a novel therapeutic approaches in the regulation of tumor progression and metastasis." (PMID 36467687, 2022). "As expected, high expression levels of C1QBP are inversely correlated with tumor patients’ prognosis, making C1QBP a valuable independent prognostic marker of outcomes in tumor patients." (PMID 36467687, 2022). "C1QBP plays critical role in mitochondria protein synthesis, maintenance of oxidative phosphorylation, and tumor metabolism reprogramming, suggesting the importance of C1QBP in metabolism." (PMID 35693733, 2022). "We found that these inhibitory receptors exhibited higher expression levels in tumor-infiltrating C1qbp+/− T cells than the corresponding WT cells." (PMID 36467687, 2022). "C1QBP expression is dysregulated in several tumours and is involved in promoting cell migration and tumour growth in melanoma." (PMID 35366893, 2022). "Consistent with the results from LSCC cells, higher C1QBP expression was observed in LSCC tissues compared to levels detected in the tumour-adjacent normal tissues." (PMID 35366893, 2022). "In contrast, C1QBP silencing attenuated tumor progression and metastasis in vivo by modulating the tumor microenvironment through inhibiting tumor angiogenesis and macrophage infiltration." (PMID 36467687, 2022). "On the contrast, C1qbp knocking down dampens mitochondrial adaptation and metabolic flexibility, which is responsible for tumor repression." (PMID 36467687, 2022). "C1QBP is involved in tumor progression and metastasis, making it an attractive, actionable target against cancer, bringing to the development of monoclonal antibodies (mAbs)." (PMID 36467687, 2022). "The enhanced protein expression of C1QBP in HCC tumor tissues was further confirmed based on the data obtained from Human Protein Atlas (HPA) database." (PMID 35711850, 2022). "Our findings suggest that C1QBP is a novel mediator of RCC tumor progression and targeting C1QBP/XDH provides a potential treatment strategy for RCC." (PMID 35693733, 2022). "In vivo, orthotopic tumor xenografts assay was performed to investigate the role of C1QBP in RCC progression." (PMID 35693733, 2022). "C1QBP overexpression promotes mitochondrial plasticity to endow tumor cells with proliferation and malignant progression." (PMID 36467687, 2022).
tumor (continued). "Next, primary tumors were isolated from mice in these two groups, and the tumor weight was lower in the C1QBP overexpression group, suggesting that C1QBP played an important role in RCC tumor growth in vivo." (PMID 35693733, 2022). "In this regard, manipulation of C1QBP has been shown to adjust the competitive balance between tumor cells and immune cells." (PMID 36467687, 2022). "To determine the role of C1QBP in the RCC progression in vivo, we constructed an orthotopic tumor xenograft model with implantation of stable C1QBP overexpression and control ACHN cells with luciferase into the left kidney capsule of BALB/c nude mice." (PMID 35693733, 2022). "This review discusses the dual roles of C1QBP for mitochondrial function in tumor malignancy and immune cells." (PMID 36467687, 2022). "For example, C1QBP located on the cell surface interacts with tumor homing peptide, Lyp-1, which specifically recognizes an epitope in tumor cells." (PMID 36467687, 2022). "IHC and ISH analyses further indicated that circMTCL1 and C1QBP were both significantly decreased in the sh-circRNA group as compared to the control group in the subcutaneous or metastatic tumours." (PMID 35366893, 2022). "Tumor cells depend on C1QBP for progression and therapeutic resistance, while immune cells also depend on it for a persistent and powerful antitumor response." (PMID 36467687, 2022). "In this regard, C1qbp knocking down exacerbated the tumor-infiltrating T cells exhaustion, leading to a reduced antitumor immune response." (PMID 36467687, 2022). "P32, also known as complement component 1 Q subcomponent-binding protein (C1QBP), has previously been reported to be expressed in tumor cells and tumor-associated endothelial cells." (PMID 34884607, 2021). "After the xenograft-TNBC models were established and the average tumor volumes reached 150 mm3 (in both control and shC1QBP groups), PTX resistance was subsequently tested in association with C1QBP depletion." (PMID 33708767, 2021). "We identified p32/gC1qR/HABP/C1qBP to be the receptor for the CGKRK peptide, expressed in high levels on the surface of tumor cells and tumor-associated endothelial cells." (PMID 34127674, 2021). "As the description above, not limited to C3, a series of complement related proteins, such as Serpind1, Cfd, C5, C1qbp, etc., were upregulated in tumor with YB1 treatment." (PMID 34489962, 2021). "Knockdown of C1QBP reduces the cellular respiration of mitochondria, shifts metabolism from oxidative phosphorylation to glycolysis and suppresses tumor formation in vivo." (PMID 30991713, 2019). "Overexpressed C1QBP in cancers has been targeted by antibodies, A-tumor-homing peptide, LyP-1, and small molecules for therapeutic applications." (PMID 30991713, 2019). "Inhibition of C1qbp was reported to suppress the growth of the tumour cells, which presents C1qbp as a potential drug target." (PMID 30872665, 2019). "In a word, it is tissue specificity of C1QBP expression and C1QBP appears to be tumor suppresser in RCC." (PMID 28428626, 2017). "This genome-wide CRISPR screen showed that blocking the vitronectin (Vtn)-complement C1Q binding protein (C1qbp) interaction could increase macrophage phagocytosis, inhibiting tumour progression in vivo." (PMID 40650785, 2025). "Although the data regarding the degradation of C1QBP may possess certain limitation, PDBAG1‐mediated down‐regulation of C1QBP protein has been observed in various tumour cell lines in this study." (PMID 39748215, 2025). "C1QBP and PFKP are critical cuproptosis-related genes in LUAD, with their high expression linked to poor prognosis and increased tumor progression; targeting these genes could offer potential therapeutic strategies for managing LUAD." (PMID 41041346, 2025).
tumor (continued). "Meanwhile, at the resting condition of macrophages, C1qbp was rarely detected on macrophage plasma membranes, but stimulation with tumor supernatant or co-culture with tumor cells significantly enhanced the transfer of C1qbp to the plasma membrane in macrophages." (PMID 38773982, 2024). "To further confirm the binding of tumor-derived Vtn with C1qbp on macrophage plasma membranes, we co-cultured the control Raw264.7 or C1qbp-knockdown Raw264.7 cells, in which C1qbp was hardly detectable, with the conditional medium (CM) from 4T1 cells expressing Myc-tagged Vtn." (PMID 38773982, 2024). "Through both in vitro and in vivo experiments, C1QBP is substantiated to exert a profound impact on cell proliferation, anti‐apoptotic responses, migration, invasion, tumor immune microenvironment modulation, cisplatin resistance promotion, and potentially on macrophage polarization." (PMID 39553438, 2024). "The high recurrence of genes like C1QBP and RPS3A in Luminal A, USP31 and RRM1 in Luminal B, and PSMD8 and YME1L1 in Basal subtypes highlights the subtype-specific regulatory networks that underlie tumor progression." (PMID 39596229, 2024). "Based on the previously reported role of Vtn-C1qbp signaling in tumor immune response, we further investigated whether Vtn knockdown and anti-CD47 antibody treatment have a synergistic anti-tumor effect." (PMID 38773982, 2024). "Noteworthily, our in vitro and in vivo experiments validate these bioinformatics discoveries, with C1QBP observed to possess attributes that confer resistance to apoptosis, enhance tumor migration and invasiveness, and play a critical role in developing cisplatin resistance in OS." (PMID 39553438, 2024). "Our co-immunoprecipitation experiments revealed for the first time that Vtn secreted by tumor cells could bind C1qbp on macrophage plasma membranes." (PMID 38773982, 2024). "Moreover, the expression of C1QBP and XDH was lower in RCC tumors compared with the tumor-associated normal tissues, and their down-regulation was associated with higher Fuhrman grade." (PMID 35693733, 2022). "C1QBP knockdown tumor cell lines showed decreased complex I, III, IV, and V subunit levels." (PMID 35310974, 2022). "C1QBP may be pivotal in tumor cell survival, growth and metastatic invasion through interacting with critical molecules, including those of the complement and kinin systems, in the tumor cell microenvironment." (PMID 35310974, 2022). "C1QBP can also be found at the cell surface of angiogenic endothelial cells besides tumor cells." (PMID 36467687, 2022). "Moreover, a remarkable increase of C1QBP expression was observed in HCC tumor samples compared with paired or unpaired normal tissue samples was observed in the TCGA-LIHC database and other databases." (PMID 35711850, 2022). "C1QBP promotes mitochondrial plasticity to impact tumor metastasis and their therapeutic response." (PMID 36467687, 2022). "Next, bioinformatic analyses were carried out on three datasets downloaded from the GEO database (GSE14520, GSE36376 and GSE76427) and one dataset from ICGC database, respectively, for systematically studying the differential expression of C1QBP in non-tumor and HCC tissue samples." (PMID 35711850, 2022). "Although a variety of studies have shown that Complement C11 binding protein (C1QBP) may play a tumor-promoting or tumor-suppressive role in cancer, the functions and mechanisms of C1QBP in HCC progression are under-investigating." (PMID 35711850, 2022). "Furthermore, siRNA-mediated C1QBP knockdown enhanced tumor cell death in response to cisplatin treatment." (PMID 36467687, 2022). "In line with earlier results, C1QBP levels were significantly higher in HCC tissue samples compared with non-tumor samples, indicating that C1QBP might be actively involved in the development and progression of HCC." (PMID 35711850, 2022).
tumor (continued). "Furthermore, tumor-derived exosomes that contain different transmitters, such as the CD44v6/C1QBP complex, have exhibited significant facilitation of the activation of HSCs and thus direct CAFs to induce tumor metastasis as well as ECM remodeling." (PMID 34635121, 2021). "Furthermore, we tested C1qbp mRNA expression in 42 distinct CRC tumor samples of different tumor grades and stages." (PMID 33102234, 2020). "Mitochondrial C1qbp may also be responsible for the tumour-promoting property by increasing the energy for the growth of the cells and allowing glutamine addiction." (PMID 30872665, 2019). "Therefore, we hypothesise that the reduction of C1QBP may cause mitochondrial damage, leading to compromised cellular function and the passive activation of HIF‐1α in tumour cells, ultimately enhancing glycolysis to compensate for the energy deficit." (PMID 39748215, 2025). "Similarly, C1QBP involved in the mitochondrial function and immune regulation with consistent literature regarding its involvement in supporting tumor cell survival, modulating immune cell dynamics, and contributing to immune escape mechanisms presented higher abundance in PDAC within this study." (PMID 41007761, 2025). "Similarly, blocking the interaction between tumor cell-secreted vitronectin (Vtn) and its receptor C1qbp on macrophages effectively counteracts the “don’t eat me” signal, augmenting tumor cell phagocytosis and suppressing triple-negative breast cancer progression." (PMID 41459510, 2025). "Furthermore, C1QBP modulates tumor proliferation and metastasis." (PMID 36467687, 2022). "Thus, the question whether C1QBP would regulate mitochondrial biogenesis to further impact tumor stemness will be of interest." (PMID 36467687, 2022). "C1QBP may be needed to sustain tumor cell growth by maintaining respiration and OXPHOS." (PMID 35310974, 2022). "In summary, while research on cuproptosis-related genes in LUAD is still evolving, C1QBP and PFKP appear to play significant roles in tumor progression." (PMID 41041346, 2025). "Our results demonstrate that C1QBP is significantly upregulated in HCC tissues and radioresistant HCC cells, consistent with previous reports that link C1QBP to tumor progression and therapy resistance in various cancers." (PMID 40429658, 2025). "P32, also known as gC1qR/HABP/C1qBP, is a mitochondrial protein that acts as a receptor for CGKPK and is expressed on surfaces of tumor cells and endothelial cells involved in tumor angiogenesis." (PMID 39506843, 2024). "We also reached consistent conclusions that C1QBP inhibited tumor growth and increased expression of XDH and pro-apoptotic related protein in mice orthotopic tumor xenografts model." (PMID 35693733, 2022). "On this note, the authors showed that C1QBP held the activity of protein kinase C and modulated EGF-induced cancer cell chemotaxis, which thus impacted tumor cell migration." (PMID 36467687, 2022). "Since C1QBP and KNG1 are supposed to be involved in the crosstalk between KLK11 and CCDC25, their role in tumor metastasis should be explored." (PMID 34067437, 2021). "As C1QBP regulates the balance between OXPHOS and glycolysis in TNBC, the relationship between C1QBP and TP53NIP1 in tumor cell stress needs further investigation." (PMID 33708767, 2021). "In addition, PDBAG1 also down‐regulates C1QBP expression levels in both murine TNBC cell lines (4T1 and E0771) and blood tumour cell lines (Jurkat and THP‐1)." (PMID 39748215, 2025). "Finally, we validated the tissue expression and in vitro functions of two genes, C1QBP and PFKP, which were found to be involved in copper ion metabolism in LUAC and affect tumor cell proliferation and invasion capabilities." (PMID 41041346, 2025). "Thus, PA28γ stabilizes C1QBP via N-terminal interaction to drive mitochondrial OXPHOS and tumor progression, highlighting its potential as a therapeutic target." (PMID 40736231, 2025).